IL1B (interleukin 1 beta)
Diseases named in the same sentence as IL1B in open-access papers (continued):
Sharing a sentence is not in itself a finding about the gene and the disease.
leukemia (continued). "CCK8 assay showed that the proliferation was inhibited in IL-1β siRNA transfected leukemia cells compared with controls after treatment with Ara-C or DNR, though IL-1β knockdown alone has no statistical effect on THP-1 cells." (PMID 34211462, 2021). "Our results showed that the apoptosis proteins, cleaved caspase 3, cleaved caspase 9 and Bax, were aberrantly over-expressed after knocking down IL-1β in leukemia cells by siRNA, while Bcl-2 onco-protein was down-regulated." (PMID 34211462, 2021). "Here, we demonstrated that NF-κB inhibitor Bay11-7082 decreased the secretion of IL-1β and IL-18 from leukemia cells and down-regulated the protein expression of pNF-κB, pro-caspase-1, pro-IL-1β, active caspase-1 and IL-1β." (PMID 34211462, 2021). "As expected, our results showed that Z-YVAD-FMK decreased the secretion of IL-1β and IL-18 into culture medium of leukemia cells." (PMID 34211462, 2021). "On the other hand, the analysis of leukaemia cell/CP fibroblast co‐cultures also showed that CD19+ blasts expressed IL1B, TGFB1, VEGFA, and the metalloproteinase ADAM10, and this expression was significantly upregulated in the presence of CP fibroblasts." (PMID 32686161, 2020). "Accordingly, administration of DNR but not ARA-C promoted a significant increase of IFN-γ (p < 0.05), IL-1β (p < 0.01), IL-2 (p < 0.001), and IL-12 (p < 0.05) in the serum of leukemia-bearing mice." (PMID 29312358, 2017). "The results presented in this report support these findings, and importantly, demonstrate that ARC regulates leukemia/stromal interactions likely via several NFκB/IL1β-mediated receptor/chemokine axes that seem to further support AML cell chemoresistance." (PMID 26956049, 2016). "Specifically, CCL2 is one of the most highly expressed chemokines in BM-derived MSCs, and its expression is regulated through ARC in MSCs and by ARC-induced IL1β from leukemia cells." (PMID 26956049, 2016). "Expression of these chemokines in MSCs increased by AML cells in an ARC/IL1β-dependent manner; likewise, IL1β expression was elevated when leukemia cells were co-cultured with MSCs." (PMID 26956049, 2016). "For example, TNF-α is expressed at a high level by AML blasts and mainly enhances production of the cytokines IL-1β and GM-CSF in terms of leukemia growth control; other studies demonstrated that TNF-α can induce apoptosis in leukemic cells." (PMID 26516703, 2015). "The RT-PCR results confirmed the greater expression of CCL2, ICAM1, IL8 and IL1B in BMSCs co-cultured with leukemia cells compared with BMSC mono-cultures." (PMID 24304929, 2013). "The cells were then transfected with mRNA from the leukemia cell line Jurkat E6 by electroporation and incubated for additional 24 h or 2 days in the presence of pro-inflammatory cytokines (TNFα, IL-1β, IL-6 and PGE2) to obtain mature DCs." (PMID 17608923, 2007). "In leukemias, there is an overproduction of IL-1β cytokines and other inflammatory cytokines, such as TNF-α and IL-6, which may be associated with tumor progression." (PMID 37577033, 2023). "Moreover, IL-1β knockdown significantly increased the apoptosis rate of leukemia cells after treatment of chemotherapy." (PMID 34211462, 2021). "We applied AML leukemia cells with NF-κB inhibitor Bay11-7082, and found that Bay11-7082 significantly decreased the protein levels of LPS+ATP induced pNF-κB, pro-caspase-1, pro-IL-1β, cleaved caspase-1 and cleaved IL-1β (right column 1 and 3)." (PMID 34211462, 2021). "All these findings illustrate the evidence that highly activated NLRP3 inflammasome in AML bone marrow leukemia cells correlates with poor prognosis and may act through IL-1β pathway in AML." (PMID 34211462, 2021). "It is clear that the combined increased gene expression of IL-1β, the secretion of IL-10, GM-CSF, and TNFα, and decreased secretion of IL-8 contribute to the anti-proliferative effects of carnosine on U937 promonocytic leukemia cells." (PMID 33809496, 2021).
leukemia (continued). "Interestingly, blockade of these cytokines or their respective receptors has shown promising clinical outcomes in several types of cancers, including leukemia (anti-IL-7Rα), lung (anti-IL-1β) and skin (anti-TGF-β1) cancers." (PMID 34298791, 2021). "The leukemia inhibitor GC is composed of interleukin-1beta, IL1B, and interleukin-8 (IL9) (LIF)." (PMID 34745009, 2021). "Additionally, high IL-1β levels can contribute to leukemia progression, altering the anti-tumor immune response and contributing to myeloid-derived suppressor cell (MDSCs) generation." (PMID 32443460, 2020). "We found that luteolin decreased the levels of interleukin- (IL-) 6, IL-8, soluble intercellular adhesion molecule-1 (sICAM-1), and monocyte chemoattractant protein-1 (MCP-1) and attenuated adherence of the human monocytic leukemia cell line THP-1 to IL-1β-stimulated ARPE-19 cells." (PMID 33122970, 2020). "To determine the biological consequence of IL1β blockade in leukemia/stromal interactions, we next performed an adhesion/migration assay and found that inhibition of IL1β by IL1βRA suppressed the adhesion/migration of leukemia cells to MSCs." (PMID 26956049, 2016). "To determine whether ARC-regulated IL1β, which has a role in leukemia-stromal interactions, also impacts chemosensitivity, we next treated OCI-AML3 cells with Ara-C in the absence or presence of MSCs and/or IL1βRA." (PMID 26956049, 2016). "Furthermore, we proposed to evaluate the patterns of dendritic cell lineages and of a subset of immunomodulatory cytokines (IL-10, TNF-α, IL-6, and IL-1β) during the course of ITD+ leukemia." (PMID 23616009, 2013). "Furthermore, an independent Syk inhibitor, entospletinib, which is currently in use in clinical trials for leukemia, also reduced IL-1β release from T. gondii-infected monocytes in a dose-dependent manner, without affecting parasite infection efficiency or viability." (PMID 31449558, 2019). "Moreover, cytokines released from leukemia blasts (e.g., IL-1β) may alter the proportions of NK cells and ILC3, suggesting the possibility that leukemia may skew the ILC repertoire." (PMID 27242795, 2016). "In that regard, we evaluated if cytokines (IL-10, TNF-α, IL-6, and IL-1β) proposed by several groups as indicators of a broad range of immunopathological conditions affecting cancer could also serve as potential biomarkers to predict ITD+ leukemia relapse." (PMID 23616009, 2013). "The comparison revealed consistent trends, with BCP‐ALL and MLL‐ALL bearing the highest NLRP3 expression, T‐ALL exhibiting the lowest IL‐1β expression and a persistent increase in CASP1 expression across the leukemia panel." (PMID 40104043, 2025). "γ-Mangostin effectively suppresses leukemia cells by inducing ICD, which is characterized by increased expression of HSP90B1, ANXA1, and IL1B." (PMID 38627685, 2024). "In this study, seven cytokines (IL1β, IL4, IL6, IL8, GM-CSF, TNFα, and VEGF) were measured in neonatal blood spots from 1,020 ALL cases and 1,003 controls in the California Childhood Leukemia Study." (PMID 39658797, 2024). "In human differentiated THP-1 cells (a human leukemia monocytic cell line), knockdown of PGAM5 stimulated TNFα and IL-6 secretion in naïve macropahges and increased TNFα, IL-6 and IL-1β in macropahges treated with IL-4 and IL-13 (M2 macrophage)." (PMID 37605246, 2023). "Res and ω-3 PUFA reduced IL-1β, IL-6, TNF-α, CXCL10/IP-10, CCL13/MCP-4 and CCL20/MIP-3α in LPS/IFN-γ activated human leukaemia THP-1 cells, which is indicative of a dampening effect on M1 macrophages." (PMID 35884829, 2022). "In the post-index group, the concentration of IL-1β and TNF in head and neck carcinoma were significantly higher than those in leukemia (p < 0.01 and p < 0.01, respectively)." (PMID 35476641, 2022). "Among all leukemia subtypes, CD33 exhibited a robust enrichment in AML and CML (chronic myelogenous leukemia), while IL1B correlated best with pediatric ALL and considerably with AML." (PMID 35646901, 2022).
leukemia (continued). "Taken together, our data suggest that inactivation of both IL1β and TNF signaling is more effective in facilitating NF-κB inhibitor-induced repression of leukemia development." (PMID 28039479, 2017). "Previous studies have shown that exogenous HMGB1 of levels reach as high as 200 ng/ml during anti-neoplastic immunity of leukemia chemotherapy and induce TNF-α and IL-1β secretion." (PMID 28404891, 2017). "Correlating with the increased monocyte viability, the leukemia supernatant (1:3 dilution) induced the secretion of IL-10, TNF-α, IL-6, and IL-1β in both experiments." (PMID 23616009, 2013). "Prior to our work, supernatants of FD leukemia samples containing IL-6 and IL-10, TNF-α, and IL-1β were shown to trigger a block in DC differentiation in vitro." (PMID 23616009, 2013). "Zinc deficiency increases the expression of cytokine-related genes (TNF; IL1B; IL8) in leukemia cell-lines." (PMID 22191060, 2011). "Caspase-1 (CASP1) is best known for regulating IL-1β processing and pyroptosis; however, its role in leukemia has not been clearly defined." (PMID 41500224, 2026). "ARC upregulated IL1β in AML cells and increased the levels of CCL2, CCL4, and CXCL12 in MSCs by activating the NFκB pathway, thereby promoting the migration and adhesion of leukemia cells to MSCs." (PMID 39351758, 2024). "To determine if CARD8 inflammasome activation can occur during HIV-1 infection in the absence of small molecule-induced HIV-1PR dimers, we infected the human leukemia monocytic cell line THP-1 at a multiplicity of infection (MOI) <1 and assayed for cell death (left) or IL-1β secretion (right)." (PMID 37417868, 2023). "It has been demonstrated that MSA-2 can activate mouse and human STING genes, induce the phosphorylation of TBK1 and IRF-3 and activate the STING signal pathway in the human leukemia monocytic cell line (THP-1 cells) and induce the expression of IFN-β, IL-1β and TNF-α via the action of TBK1." (PMID 38005816, 2023). "In addition, GLA significantly reduced the release of histamine and β-hexosaminidase, calcium influx, cytokine (IL-4, TNF-α, IL-1β, IL-13, and IL-8) production in the RBL-2H3 (rat basophilic leukemia cells), and RPMCs (peritoneal mast cells) in vitro." (PMID 34007295, 2021). "Compared with the controls, the end of network for AML patients was pointed from IL-1β to IL-1R and from NLRP3 to NF-κB, which indicates that NLRP3 inflammasome may act through IL-1β or NF-κB in AML leukemia cells." (PMID 34211462, 2021). "Furthermore, human recombinant IL-1β and/or IL-18 were added into the culture medium of primary AML leukemia cells." (PMID 34211462, 2021). "CCK8 results showed that IL-1β or IL-1β+IL-18 significantly stimulated the proliferation and inhibited the apoptosis of leukemia cells, but IL-18 alone had no obvious effects." (PMID 34211462, 2021). "Our results showed that the culture medium of NLRP3-activated THP-1 cells inhibited primary leukemia cells apoptosis, and the inhibitory effect had partially reversed after neutralization with anti-IL-1β, while anti-IL-18 had no this effect." (PMID 34211462, 2021). "Moreover, ELISA results showed that Bay11-7082 inhibited the secretion of IL-1β and IL-18 from AML primary leukemia cells." (PMID 34211462, 2021). "Thus, we sought to assess the expression profiles of NLRP3, CASP1, and IL‐1β in pediatric blood cancer samples, reasoning that the largest therapeutic impact of NLRP3 inhibition on cancer progression likely occurs in leukemia subtypes with the highest expression levels." (PMID 40104043, 2025). "Activation of alternative pathways, such as KRAS/RAC1/ROS/NLRP3, in leukemia cells or non-hematopoietic cells may also lead to the production of pro-inflammatory IL-1β that promotes leukemia cell proliferation in an autocrine fashion." (PMID 35460465, 2022).
leukemia (continued). "Although this inhibitory effect of caspase-1 on autophagy has only been demonstrated in Prion disease and during Pseudomonas aeruginosa infection, it might also be involved in the pathogenicity of leukemia, which is characterized by high NLRP3 activity and IL-1β secretion." (PMID 33525345, 2021). "Interestingly, exposure of human leukemia monocytic cells to Aedes aegypti salivary gland extract results in the downregulation of innate immune, antiviral, and inflammatory-related genes, including NF-kB, IFN-β, NLRP3, and subsequently IL-1β and IL-6, among others, at 24–36 hours." (PMID 40272158, 2025). "A mutant lacking the mymA operon induced significantly less IL-1β, IL-6, RANTES, and MCP-1 in human THP-1 monocyte-like leukemia cells, consistent with our findings of diminished immune responses in primary mouse macrophages by the Tn:Rv3087 mutant." (PMID 21170273, 2010).
synovitis (68 papers, 2006 to 2026). Inflammation of a synovial membrane. "Inflammatory cytokines (e.g. TNF-α, IL-17, IL-1β and IL-6) are known to be pathogenic factors triggering joint diseases and established synovitis." (PMID 34950033, 2021). "Synovitis-associated pathological alteration of the joints causes the release of proinflammatory cytokine mediators, such as interleukin 1β (IL-1β) and tumor necrosis factor-α (TNF-α)." (PMID 34681754, 2021). "Overall, we demonstrated that p21-deficient CAIA mice were susceptible to joint cartilage destruction and severe synovitis via IL-1β- and TNF-α-induced inflammation in vivo." (PMID 34131243, 2021). "Synovitis-induced pathological alteration causes the release of proinflammatory cytokines such as IL-1β and TNF-α." (PMID 34681754, 2021). "Our results provide evidence of LLLT-dependent reduction of IL-1β, IL-6 and TNFα, and the therapy's ability to inhibit proliferation of inflammatory cells makes it a suitable treatment for synovitis associated with the early stages of OA." (PMID 24028507, 2013). "Synovitis was caused by persistent inflammatory responses, which were resulted from the increased number of inflammatory cells and the increased secretion of various inflammatory mediators, such as IL-1β, IL-6 and IL-17." (PMID 32256686, 2020). "Moreover, RT-qPCR results suggested that in all types of synovitis caused by meniscal tears, the transcription level of IL-1β in the anterior medial region was higher than that in the anterior lateral and suprapatellar regions, and this difference was statistically significant." (PMID 38734632, 2024). "In that study, they have demonstrated that Arg2 overexpression in mouse joint tissues causes OA with synovitis and loss of glycosaminoglycans in articular cartilage followed by upregulation of pro-inflammatory products, although, their data show ablation of Arg2 promoted IL-1β caused NO production." (PMID 31979015, 2020). "This study compared the clinical and biochemical effects of intra-articular triamcinolone acetonide (TA) and autologous conditioned serum (ACS) in an equine model of IL-1β-induced synovitis." (PMID 42121792, 2026). "Regarding the IL-1β concentrations, it should be noted that IL-1β is used to induce equine synovitis in vivo." (PMID 40496923, 2025). "Our findings demonstrated that the IL-1β sticky-trap effectively delayed OA progression and reduced synovitis in the DMM model." (PMID 40264709, 2025). "Histological analyses at 10 weeks post-surgery showed that the IL-1β sticky trap significantly reduced joint OA and synovitis compared to sham and other DMM control groups." (PMID 40264709, 2025). "During the clinical phase, TNF-α, IL-6, and IL-1β drive synovitis by activating macrophages and fibroblast-like synoviocytes, while also promoting RANKL (Receptor Activator of Nuclear factor κB Ligand) expression and osteoclast differentiation." (PMID 41010616, 2025). "Our findings demonstrate that treatment with JTQBG significantly reduces the levels of IL-1β and IL-18, suggesting its potential involvement in regulating the NF-κB signaling pathway in synovitis." (PMID 38545550, 2024). "The cytotoxicity of CA was assessed using a CCK-8 assay in human IL-1β pretreated chondrocytes and synoviocytes, which serve as in vitro models of OA and synovitis." (PMID 39684628, 2024). "We discovered that DPA, a main component of omega-3 fatty acids, had a potential therapeutic effect on synovitis by significantly inhibiting the transcription and expression of IL-1β and IL-6 in RAW264.7 macrophages." (PMID 38734632, 2024). "The results indicate that both IL-1β and IL-6 play pivotal roles in synovitis pathogenesis, with distinct expression levels across various subtypes." (PMID 38734632, 2024). "The activation of NLRP3 inflammasome can induce the secretion of proinflammatory cytokines IL-1β and IL-18, leading to the aggravation of downstream inflammatory response and accelerating the occurrence of synovitis in KOA." (PMID 37065495, 2023).